PIK3CA (phosphatidylinositol-4,5-bisphosphate 3-kinase catalytic subunit alpha)
Diseases named in the same sentence as PIK3CA in open-access papers (continued):
Sharing a sentence is not in itself a finding about the gene and the disease.
squamous cell carcinoma (continued). "The PIK3CA alterations appear to be present in squamous cell carcinomas regardless from which organ they originate." (PMID 29371888, 2018). "More importantly, the amplification of PIK3CA was detected in over 30% of squamous-cell carcinoma biopsy." (PMID 28427230, 2017). "BRAF CNGs (13%) were more common in adenocarcinoma subtype and PIK3CA CNGs (36.4%) were more frequent in squamous cell carcinoma as compared to the other subtypes." (PMID 19238210, 2009). "In general mutations were more common in adenocarcinoma subtype and relatively rare in squamous cell carcinomas except for PIK3CA which was more common in squamous cell carcinomas, as also occurs in tumors." (PMID 19238210, 2009). "However, PIK3CA and amplifications and mutations are also frequently detected in NSCLC, in 3.7–19% of cases, with 2.9–6.2% in adenocarcinoma and 8.9–33% in squamous cell carcinoma." (PMID 38347643, 2024). "Although many articles have even reviewed papers investigating or summarizing the biological and clinical roles of mutated PIK3CA in cancer, the majority of these studies were conducted in adenocarcinoma rather than in squamous cell carcinoma (SCC)." (PMID 38616230, 2024). "PIK3CA is amplified in 13.4% of squamous cell carcinoma only." (PMID 35585228, 2022). "Interestingly, USP13 sits on chromosome 3q26.33, in the so-called 3q26 ‘OncCassette’, a common amplicon that is found in most squamous cell carcinomas and includes the oncogene PIK3CA." (PMID 33627786, 2021). "As PIK3CA and FBXW7 genes are significantly mutated in other HPV associated squamous cell carcinomas, they could act as driver events in this histological type of cancers." (PMID 29416628, 2018). "PIK3CA mutations were more common in squamous cell carcinomas than in non-squamous cell tumors (15.3% vs 7.3%, of P < 0.01)." (PMID 26358014, 2015). "In addition to mutations, PIK3CA is frequently amplified in NSCLC, particularly in men, smokers, and also in squamous-cell carcinoma." (PMID 22928112, 2012). "In addition, PIK3CA mutations occurred more frequently in squamous cell carcinomas than in non-squamous cell tumors (15.3% vs. 7.3%, P = 0.01)." (PMID 26358014, 2015). "In another study, PIK3CA amplification was significantly associated with smoking history and histological type, which was more frequent in smokers compared to never smokers, and in squamous-cell carcinoma compared to adenocarcinoma." (PMID 22928112, 2012).
squamous cell carcinoma (continued). "Of note, squamous cell carcinoma cases had enrichment of fusions involving FGFR1 (0.9% vs 0.3%), FGFR3 (0.8% vs 0.2%), and PIK3CA (0.5% vs <0.01%)." (PMID 39664186, 2024). "However, a systematic review indicated that the effects of PIK3CA mutations on survival outcomes are unclear, and the majority of the included studies support a the potentially negative effect, primarily among those with squamous cell carcinoma." (PMID 37884919, 2023). "This PIK3CA-EGFR/KRAS co-mutation was more common in never smokers than in current or former smokers (p = 0.039), and in adenocarcinoma than in squamous cell carcinoma (p<0.0001)." (PMID 24533074, 2014). "We only found EGFR (8.0%), c-Met (2.8%), and PIK3CA (2.6%) alterations in the non-smoker with squamous cell carcinoma (SCC) subgroup." (PMID 22768234, 2012). "Similar to the previous studies, we found that PIK3CA amplification was significantly associated with smoking history and histologic type, which was more prevalent in smokers compared to never smokers, and in squamous cell carcinomas compared to adenocarcinomas in PIK3CA wildtype group." (PMID 24533074, 2014).
prostate carcinoma (83 papers, 2010 to 2025). A carcinoma that arises from epithelial cells of the prostate gland. "Previous research has linked PIK3CA mutations to enhanced immune resistance and increased PD-L1 expression in breast and prostate cancers." (PMID 40724985, 2025). "Mutations in PI3K catalytic subunit genes, especially p110α (PIK3CA), were frequently identified in prostate cancer with concurrent PIK3CA mutation and loss of phosphatase and tensin homolog (PTEN) accelerating tumorigenesis and promoting CRPC in mouse models." (PMID 38287309, 2024). "For example, alterations in metabolism related to prostate cancer were identified and the actual influence of PIK3CA mutations on lipid metabolism clarified by lipidomic approaches." (PMID 39202486, 2024). "In prostate cancer, PIK3CA oncogenic mutations were found to cooperate with PTEN loss to accelerate tumor growth and facilitate castration resistance." (PMID 36765741, 2023). "Mutations in the PIK3CA oncogene, in which the function is associated with cell differentiation and migration, have been described in multiple human cancers, including prostate cancer." (PMID 37021836, 2023). "In human prostate cancer, mutations and inactivation of Pten are more common than amplifications and activation of PIK3CA, PIK3CB, PIK3R1, and AKT1." (PMID 36358740, 2022). "In breast cancer, activating PIK3CA mutations are dominant drivers of PI3K signaling whereas in PTEN-deficient prostate cancer, such activity is reported to be driven by p110β16,17." (PMID 34417459, 2021). "Previous work has shown that p110α isoform-specific PI3K inhibitors can suppress Pik3ca mutant prostate cancer, whereas a p110β/δ inhibitor, or combined p110α/β blockade improves therapeutic outcome in Pten-deficient (p110β-dependent) prostate cancers." (PMID 32630372, 2020). "In the prostate cancer datasets analyzed, PIK3CA mutation and high-level gene amplification occur in up to 4% and 9% of cases respectively, although high-level amplification has been observed previously in as many as 29% of cases." (PMID 32630372, 2020). "For example, among newly diagnosed US patients of type HLA-C*04:01, 88 prostate cancer patients are expected to carry the mutation PIK3CA:R88Q, even though its observed frequency in the PRAD study is as low as 0.2%." (PMID 31775766, 2019). "A first study showed that PIK3CA mutation correlates with poor prostate cancer prognosis and induces prostate cancer development in murine models." (PMID 31366128, 2019). "PIK3CA is frequently mutated in prostate cancers, and many of these mutations result in activation of PI3K9." (PMID 31551414, 2019). "A variety of transplanted models with ipatasertib treatment showed effective antitumor activity, including PTEN-deficient prostate cancer and in metastatic breast cancer with PIK3CA H1047R mutation." (PMID 30185800, 2018). "Also, PIK3CA mutation leads to prostate cancer in mice and correlates with poor prostate cancer prognosis." (PMID 37596643, 2023). "Additionally, another study reported that mutations in PIK3CA were correlated with poor survival in prostate cancer." (PMID 36095024, 2022). "Using this method, we reveal a severe skewing in acyl chains in phosphoinositides in Pten-deficient prostate cancer tissues, extracellular mobilization of phosphoinositides upon expression of oncogenic PIK3CA, and a unique profile for exosomal phosphoinositides." (PMID 35013169, 2022). "Therefore, according to our findings, it is unlikely that in Jordanian population SPOP and PIK3CA hotspot mutations contribute to prostate cancer or they do but in a much lower percentage." (PMID 33247697, 2020). "Thus, we identified that the PTEN-ARID4B-PI3K regulatory axis underlies the predictive power of the PTEN/ARID4B/PIK3CA signature for tumor recurrence in prostate cancer patients." (PMID 31551414, 2019). "Our findings suggest that specific genetic mutations, including PIK3CA, LRP6, LRRK2, and BRCA2, are linked to prostate cancer metastasis and BCR." (PMID 40660132, 2025).
prostate carcinoma (continued). "TBL1XR1 is thought to regulate the expression of nuclear hormone receptor co-repressor, and tissue types in which the TBL1XR1::PIK3CA fusions were found (invasive breast carcinoma and prostate cancer) are hormonally regulated." (PMID 41123735, 2025). "Hyperactivation of the PI3K/Akt/mTOR signaling pathway in prostate cancer is mostly related to mutations in PTEN; however, other abnormalities, such as gain-of-function mutations in PIK3CA or AKT genetic aberrations, have also been detected." (PMID 38672636, 2024). "In prostate cancer, oncogenic alterations in PIK3CA and AR were enriched in TMB and bTMB≥10 samples, whereas TMPRSS2-ERG fusions were more likely to be found in TMB and bTMB<10 samples." (PMID 40027285, 2023). "Conversely, the core members (HGF, MET, and PIK3CA) were downregulated in the FOXP2 knockdown PC3 prostate cancer cells." (PMID 37668356, 2023). "We also analyzed two previously established prostate cancer cell lines, LNCaP (PTEN loss) and CWR22Pc (PIK3CA Q546R)." (PMID 34417459, 2021). "For instance, miR-202 was shown to suppress growth and metastasis in prostate cancer by targeting PIK3CA." (PMID 33002044, 2020). "Of note was PI3K family members: PIK3C2G, PIK3CA, PIK3CB, PIK3R4, Mucin family members: MUC1, MUC4 and MUC6 and other prostate cancer associated genes such as SMAD4, SOX9 and SPOP7,9,40,41." (PMID 32796921, 2020). "While PIK3CA mutant prostate cancers have been shown to respond to p110α isoform-specific inhibition, previous work by us and others has shown that targeting p110α alone in prostate cancers with PTEN loss is not efficacious, owing to p110β dependency." (PMID 33105713, 2020). "Together, these data support the importance of functional interactions between PTEN, ARID4B, and PIK3CA in human prostate cancer." (PMID 31551414, 2019). "Recent research even found that PIK3CA amplification had a correlation with poor survival of patients with prostatic carcinoma." (PMID 30918758, 2019). "The analysis of large-scale genomic studies of the TCGA and other prostate cancer databases provided evidence that in the large majority of patients CHD1 loss and PTEN deletion (as well as AKT1, AKT2, AKT3, and PIK3CA gene alterations) were mutually exclusive." (PMID 31366128, 2019). "We found that the PTEN/ARID4B/PIK3CA three-gene signature had an increased predictive power for prostate cancer recurrence compared to any individual gene alone or two genes combined." (PMID 31551414, 2019). "The biological significance is further substantiated by the existence of a PTEN/ARID4B/PIK3CA three-gene signature that improves the predictive power for prostate cancer recurrence in patients." (PMID 31551414, 2019). "In prostate cancer the PI3K/AKT pathway has been described as a key regulator in the transcription of the AR, and in breast cancer mutations at the PIK3CA gene were associated with expression of the AR in patients." (PMID 24779793, 2014). "Notably, PIK3CA mutation and PTEN loss coexist in prostate cancer patients and synergistically can cooperate in vivo to accelerate carcinogenesis and cancer progression via PAM pathway hyperactivation." (PMID 37596643, 2023). "Taken together, we have demonstrated that aberrant PI3K signaling driven by amplification or activating mutations of PIK3CA or PIK3CB are able to shift p110 isoform dependency regardless of PTEN status across multiple prostate cancer models." (PMID 34417459, 2021).
prostate carcinoma (continued). "Besides, the PIK3CA gene alteration is highly prevalent in many types of cancers such as endometrial, breast, ovarian, colorectal and prostate cancers." (PMID 33247697, 2020). "One reason may be that genetic alterations in the PIK3CA/Akt1/PTEN pathway are less frequent among Asian men with prostate cancer than among Caucasian men." (PMID 31227862, 2019). "However, this pathway is frequently activated in human prostate cancer as a result of genetic alterations that include the biallelic loss of PTEN and activating mutations in AKT1 and PIK3CA/B." (PMID 26910118, 2016). "Indeed, this pathway is deregulated in up to 65% of prostate cancers, most commonly due to PTEN loss, and less commonly related to PIK3CA amplification or mutation." (PMID 25595907, 2015). "In prostate cancer, however, activating mutations in PIK3CA or PIK3R1 have not been reported thus far." (PMID 20407443, 2010). "According to Zhang and colleagues (2018), miR-202 is downregulated in human prostate cancer tissues and cell lines, while overexpression of miR-202 significantly suppressed prostate cancer progression, demonstrating miR-202 as a tumor suppressor via direct targeting of PIK3CA." (PMID 35682549, 2022). "Importantly, PIK3CA mutant PTEN wild-type prostate cancers should not be broadly grouped with PTEN loss cancers in future AKT inhibitor clinical trials." (PMID 34417459, 2021). "High frequencies of CNAs were observed in PIK3CA, FGFR1, and EGFR in breast, ovary, pancreas, and prostate cancer samples." (PMID 38674331, 2024). "The expression of three genes (BCL2L11, PIK3CA, and XIAP) regulated in opposite directions (up/down) occurred in patients with HD and breast/prostate cancer." (PMID 37298337, 2023). "Common genetic alterations within the three prostate cancer datasets analyzed were observed in PTEN, DEPTOR, SGK3, FOXO1/3, MAP3K7, RRAGD, SESN1, PIK3CA, PIK3C2B, and PDPK1." (PMID 32630372, 2020). "For example, AR, EGFR, DDR2 and MAP2K2 were connected with mtDNA genes in prostate cancer, and TMPRSS2, NF1, PIK3CA, BRCA1 and TOP1 were the top neighbors of mtDNA genes in multiple cancer types." (PMID 32024997, 2020). "Most of the genetic alterations in ESR1, PIK3CA, AKT1, and MAPK1 were amplifications, suggesting an excess expression in prostate cancer." (PMID 30918758, 2019). "Together, our results suggest that ARID4B and HDAC1 are likely to function independently to regulate PIK3CA and PIK3R2 in prostate cancer cells." (PMID 31551414, 2019). "Similarly, TRIM24 can increase both PIK3CA and EGFR levels in human prostate cancer cell lines (LNCaP, PC-3, and C4-2), thereby facilitating the activation of the PI3K/AKT signaling pathway." (PMID 39768197, 2024). "Besides, because anticarcinogenic properties of naringenin have been reported in diverse malignant tumors prostate cancer pathway consisting of eight proteins was found: AKT1, MAPK1, IGF1R, AR, CCND1, INS, PIK3CA, IGF1." (PMID 30918758, 2019).
prostate carcinoma (continued). "In addition, PIK3CA, AKT1, and MAPK1 directly interacted with AR, which was a naringenin-mediated protein gene as well and participated in prostate cancer pathway." (PMID 30918758, 2019). "The rare PIK3C family gene fusions in prostate cancer (for example, TBXLR1-PIK3CA and ACPP-PIK3CB) show overexpression of the PI3KC genes and may be sensitive to PIK3CA inhibitors." (PMID 26684754, 2015). "Consequently, these findings have identified that selected p110 isoform-specific inhibitors may prove to hold efficacy against PIK3CA mutant and PTEN-deleted prostate cancer in the clinic." (PMID 32630372, 2020). "Therefore, a hypothesis is currently proposed that naringenin acts through a series of genes (ESR1, PIK3CA, AKT1, MAPK1, and AR) to control prostate cancer cell proliferation." (PMID 30918758, 2019).